CXCL12 (C-X-C motif chemokine ligand 12)
Diseases named in the same sentence as CXCL12 in open-access papers (continued):
Sharing a sentence is not in itself a finding about the gene and the disease.
tumor (continued). "Se@A&F induced CAFs' inactivation and remodeled the tumor microenvironment by down-regulating CXCR4 expression on CAFs' surface and inhibiting the CXCL12/CXCR4 signaling axis." (PMID 41328341, 2026). "Se@A&F induces CAFs' inactivation and remodels the tumor microenvironment by down-regulating CXCR4 expression on CAFs' surface and inhibiting the CXCL12/CXCR4 signaling axis." (PMID 41328341, 2026). "Functionally, they promote tumor progression by stimulating proliferation via FGF, IL-6, and CXCL12." (PMID 41601669, 2026). "Chemokine networks, particularly the CXCL12/CXCR4/CCR7 axis, play a crucial role in guiding tumor cells to their destinations." (PMID 41596524, 2026). "The directional movement of PMN-MDSCs is modulated by the release of C-X-C motif chemokines from tumor cells, including CXCL1, CXCL5, CXCL6, CXCL8, and CXCL12." (PMID 40722739, 2025). "Circulating levels of certain chemokines, particularly CXCL12 and CXCR4, have been investigated as potential biomarkers for tumor grading and response to therapy." (PMID 40134607, 2025). "TGF-β signaling in the TME also promotes macrophage M2 polarization, and TGF-beta activates fibroblasts to form CAFs that secrete a higher level of CXCL12, which binds to the cognate receptor CXCR4 on M2 macrophages, leading to tumor cell growth." (PMID 40124621, 2025). "In HCC, CAFs promote M2 polarization of TAMs through CXCL12 and induce secretion of plasminogen activator inhibitor 1 (PAI-1), thereby augmenting the malignant behavior of tumor cells." (PMID 40453088, 2025). "In the context of lung cancer, the signaling pathway involving chemokines, notably CXC chemokine ligand 12 (CXCL12) and its corresponding receptor, CXC chemokine receptor 4 (CXCR4), is crucial for tumor progression." (PMID 41394878, 2025). "The experimental results showed that in the hypoxic hypermetabolic zone, CXCL12 secreted by iCAFs recruited Tregs to secrete TGF-β1 through the CXCL12-ACKR3 axis, forming an immunosuppressive microenvironment and contributing to tumor immune escape." (PMID 41445742, 2025). "The tumour microenvironment has signals also derived from the tumour microenvironment, such as CXCL12, TGF-β, and IL-6, that can promote tumour survival and chemoresistance." (PMID 41002447, 2025). "Neutrophils can be recruited by chemoattractants, such as CXCL8/IL-8, CXCL12/SDF-1, VEGF, S100A8, and S100A9, secreted both from the primary tumor and from stroma cells in the PMN." (PMID 40370456, 2025). "For instance, CXCL12, secreted by tumor, stromal, and immune cells, binds to CXCR4, facilitating tumor growth, immune evasion, and therapy resistance." (PMID 40667699, 2025). "Within the TME, CXCL12 and its receptor CXCR4 promote tumour angiogenesis, sustain tumour cell survival and proliferation, and orchestrate immunosuppressive responses." (PMID 40361472, 2025). "Numerous studies revealed that chemokines such as CXCL1, CXCL2, IL-8 (CXCL8), CXCL5, CXCL12, CCL2, and MIP-1α (CCL3) promote the infiltration of neutrophil to the tumoural microenvironment." (PMID 40852716, 2025). "Tumor cells, by expressing CXCR4, respond to CXCL12 secreted by metastatic target organs (such as lymph nodes, lungs, liver and bone marrow), thereby promoting directional migration of tumor cells." (PMID 40909292, 2025). "Concurrently, this axis creates an “immune-excluded” phenotype by using stromal CXCL12 to sequester CXCR4-positive T cells, preventing their infiltration into tumor nests." (PMID 40909268, 2025). "CXCR4 is a hypoxia- and hypoxia-inducible factor (HIF)-induced receptor for the chemokine CXCL12/stromal cell-derived factor-1 (SDF-1), and is therefore a good marker for VHL mutant tumor cells." (PMID 39920694, 2025). "The results revealed that, compared with the Mod group, the IL-24 protein levels in the tumor tissues of the PVTM, PVTH, Taxol and PVTM + Taxol groups were increased, whereas the CXCL12 protein level was decreased." (PMID 40076586, 2025).
tumor (continued). "The interplay of the tumor-derived molecules like immune checkpoint ligands (PD-L1 and PD-L2), chemokines (CXCL9, CXCL10, and CXCL12), along with cytokines (TGF-β and IL-10), creates a complex immunosuppressive environment in EwS." (PMID 40242222, 2025). "CXCL12 binds to the CXCR4 and CXCR7 receptors and is involved in many physiological and pathologic processes, including immune response, cell migration and tumor metastasis." (PMID 41376630, 2025). "Studies have shown that activation of the CXCL12/CXCR4 axis can inhibit T cell infiltration and function, promoting immune evasion by tumor cells." (PMID 41346595, 2025). "CXCL12 recruits immunosuppressive TAMs and impairs T cell activation; CXCR4 blockade reduces TAM chemotaxis and delays tumor growth in preclinical models." (PMID 40936918, 2025). "Nevertheless, while CCL5 became a more dominant ligand for CCR5 in the KPC-4545 tumor, CCL4 remained a dominant ligand for CCR5 and CXCL12, CXCL10, and CXCL16 arose as major ligands for different receptors in the KPC-3403 model following anti-IL-1β treatment." (PMID 39948655, 2025). "Another key pathway is the CXCL12/CXCR4 axis, which is predominantly upregulated in hypoxic tumor regions." (PMID 41002423, 2025). "CAFs promote CSC enrichment by activating the CXCL12/CXCR4 axis and increase the migratory ability and drug resistance of tumor cells by inducing EMT, further aggravating the malignant progression of tumors." (PMID 41346633, 2025). "Tumor cells release a variety of signaling molecules, such as chemokines (e.g. CXCL12) and growth factors (e.g. VEGF), to recruit surrounding cells that support tumor growth and invasion." (PMID 41180630, 2025). "Upon being recruited to inflammatory tumor tissues in response to chemokines like CCL2, CCL5, CXCL8, and CXCL12, MDSCs rapidly produce immunosuppressive mediators, including ARG1, NO, TGF-β, and IL-10, which further impair anti-tumor immunity." (PMID 40563367, 2025). "NOX-A12 binds and neutralizes CXCL12 (SDF-1), a chemokine that attracts immunosuppressive cells and promotes tumor invasion." (PMID 41245487, 2025). "Studies indicate that CXCL12 is highly expressed in these organs, creating a chemotactic gradient that attracts CXCR4-expressing tumor cells, thereby facilitating metastasis." (PMID 41409250, 2025). "CXCR4/CXCL12 signalling is involved in lung carcinoma metastasis, where CXCR4 is a chemokine that is universally upregulated in tumour cells which migrate to the bone." (PMID 40852716, 2025). "By blocking CXCL12, NOX-A12 aims to disrupt the tumor-promoting microenvironment, hinder cancer progression, and enhance NK cell tumor infiltration." (PMID 39859231, 2025). "Chemokine–receptor interactions, such as the CXCL12/CXCR4 and HGF/c-Met axes, play central roles in guiding NSCs to tumor sites." (PMID 41264121, 2025). "Overexpression of CXCL12 and CXCR4 in ACP promotes tumor cell proliferation, migration, and invasion, primarily via the activation of the PI3K/AKT signaling pathway." (PMID 40433410, 2025). "The CXCL12/CXCR4 axis promotes epithelial-mesenchymal transition (EMT), enhances tumor cell migration and invasion, and facilitates distant metastasis through interactions with the tumor microenvironment." (PMID 40481962, 2025). "Our previous study on exp‐CAF544 cells suggested that upregulation of CXCL12 and TGF‐β in the fibroblasts supports the tumor‐promoting property in an autocrine manner." (PMID 39887653, 2025).
tumor (continued). "The hypoxic tumor microenvironment further modulates CXCR4 activity, as HIF-1α drives CXCL12/CXCR4 upregulation under low oxygen conditions." (PMID 40607416, 2025). "This review highlights chemokine-mediated mechanisms, focusing on CCR9/CCL25 and CXCL12/CXCR4 axes, which promote tumor growth, metastasis, and immune evasion via PI3K/AKT and MAPK signaling." (PMID 40607416, 2025). "The interaction of CXCL12 and CXCR4 has a broad impact on tumor cell proliferation, survival, angiogenesis, metastasis, and the tumor microenvironment." (PMID 41149503, 2025). "Studies have shown that CXCL12/CXCR4 activation leads to downstream STAT3 phosphorylation, promoting transcription of genes related to tumor growth and angiogenesis, such as VEGF, MCL-1, and BCL-XL." (PMID 40607416, 2025). "The CXCL12/CXCR4 axis NFBK1 regulates can also promote the infiltration of regulatory T cells (Tregs) and inhibit anti-tumor immunity." (PMID 40666524, 2025). "Meanwhile, CXCL12 can induce tumor cells to express CXCR4, promoting their metastasis to tissues with high CXCL12 expression, such as bone marrow and lymph nodes." (PMID 41346580, 2025). "The survival of this niche depends on the chemokine-dependent CXCL12-CXCR4 ligand-receptor signaling axis, where CAF-derived CXCL12 binds to CXCR4 on tumor cells, fostering a tumor-promoting niche that suppresses ferroptosis and promotes survival." (PMID 41450739, 2025). "They secrete chemokines such as CXCL12, which activates the CXCR4 signaling axis and spatially confines immune cells to the tumor periphery." (PMID 41341574, 2025). "Inhibits the CXCL12/CXCR4 signaling axis; reduces the accumulation of M2-TAM; suppresses tumor growth, invasion, and metastasis." (PMID 40109347, 2025). "Finally, another potential advantage may exist for the tumor in producing CXCL12 and S1P." (PMID 40155684, 2025). "Activation of CXCL12/CXCR4 triggers downstream signaling pathways, including the PI3K/AKT/mTOR and MAPK/ERK cascades, which promote tumor cell proliferation and survival." (PMID 40698080, 2025). "CAFs deposit new matrix proteins (e.g., collagens and fibronectin) and secrete growth factors (TGF-β, VEGF, PDGF, FGF2, and HGF) and cytokines (IL-6, IL-8, and CXCL12/SDF-1) that jointly reprogram the matrix and tumor behavior." (PMID 41409250, 2025). "CXCL12 and CXCR4 were expressed in the tumor stroma and on T cells, respectively, in dogs with epithelial malignant tumors." (PMID 40849508, 2025). "AMD3100, meanwhile, blocks the CXCL12/CXCR4 axis, preventing tumor cell migration and interaction with the stroma." (PMID 41348904, 2025). "CAFs also couple tumor-cell plasticity to immune suppression through mediators such as IL-6/JAK–STAT3, TGF-β, and CXCL12; after blockade of a single node, alternative routes are often activated, leading to compensatory escape." (PMID 41514658, 2025). "CXCL12, also recognized as stromal cell-derived factor 1 (SDF-1), promotes tumor proliferation and angiogenesis via the CXCL12/CXCR4 pathway." (PMID 40313969, 2025). "As chemotaxis is an important biological behavior process often used by tumor cells for metastasis and invasion CXCR4, its ligand CXCL12, and atypical receptor ACKR3 are overexpressed in many human cancers." (PMID 40427609, 2025). "Studies have further indicated that elevated expression levels of both CXCL12 and CXCR4 correlate with unfavorable prognosis in lymph node-positive cases, as well as with tumor-stroma ratio (TSR) and lymphocytic infiltration at the invasive front (LIR)." (PMID 40943634, 2025). "MDSCs are recruited to hypoxic tumor areas via CCL2 and CXCL12, express PD-L1 and suppress antigen presenting cells function affecting DC maturation and impairing T cell priming." (PMID 40963621, 2025). "By producing TGF-β, IL-6, CXCL12, and MMPs, CAFs induce EMT and modify the ECM, enhancing tumour invasiveness while creating a stiffened, collagen-rich matrix." (PMID 40361472, 2025).
tumor (continued). "The binding of CXCR4 to its ligand CXCL12 activates the CXCL12/CXCR4 axis, which regulates tumor angiogenesis, promotes tumor metastasis, mediates immune dysfunction and plays a pivotal role in downstream cell-proliferation, migration and drug resistance." (PMID 40075611, 2025). "These strategies include checkpoint inhibitors, reprogramming pro-tumour macrophages, and inhibiting TME-derived factors such as IDO, TGF-β, and CXCL12." (PMID 39592739, 2025). "As pivotal orchestrators within the TME, CAFs establish a pathological ecological network that supports tumor progression through the secretion of cytokines such as IL‐6, TGF‐β, and CXCL12." (PMID 41164803, 2025). "CAFs are central architects of the TME, driving tumor progression through extracellular matrix (ECM) remodeling, immunosuppression, and secretion of pro-tumorigenic factors (e.g., TGF-β, IL-6, CXCL12)." (PMID 40564985, 2025). "OC’s disruption of the COX-2/mPGES-1 axis reverses PGE2-mediated immunosuppression by downregulating PD-L1 expression on tumor cells (40% reduction in TNBC) and inhibiting myeloid-derived suppressor cell (MDSC) recruitment via CXCL12/CXCR4 axis blockade." (PMID 40564985, 2025). "The CXCL12/CXCR4 axis also plays a crucial role in guiding cell migration, particularly in immune cell homing, hematopoietic stem cell mobilization and tumor metastasis." (PMID 40909292, 2025). "Chemotherapy-induced hypoxia leads to the up-regulation of CXCL12/CXCR4 signalling, creating a vicious cycle that supports drug resistance and tumour regrowth." (PMID 41002447, 2025). "Preclinical work shows that NPs mediated modulation of bone marrow cytokines (e.g., IL-6, CXCL12) improves CAR-T infiltration and cytotoxicity, resulting in 40–60% superior tumor clearance compared with CAR-T alone in animal models." (PMID 41471085, 2025). "As previously discussed, the CXCL12/CXCR4 regulatory axis plays a critical role in homing and retention within the protective bone marrow microenvironment for hematologic tumor cells and normal hematopoietic stem cells (HSCs)." (PMID 40427609, 2025). "During tumor development, inflammatory signals recruit macrophages to the tumor stroma, including chemokines (e.g., CCL2, CCL5, CXCL12), cytokines (e.g., VEGF, CSF1), and complement factors." (PMID 40872551, 2025). "Approaches that target CAF signaling pathways, such as TGF-β, FGF, or CXCL12, or disrupt CAF-tumor interactions, hold promise for enhancing the effectiveness of current treatments." (PMID 40669378, 2025). "TPCs secrete factors like IL-33, CXCL12, and CXCL14, which recruit immune cells to promote a pro-tumor environment." (PMID 40784879, 2025). "Secondly, miR-222 inhibits TAM chemotaxis by targeting C-X-C chemokine receptor type 4 (CXCR4) and C-X-C motif chemokine ligand 12 (CXCL12), which ultimately suppresses tumor growth in vivo." (PMID 41357196, 2025). "Attraction of mobilized neutrophils to the tumor site is realized via chemokines CXCL1, CXCL2, CXCL5, CXCL6, and CXCL8 (IL-8) through CXCR1/2 and CXCL12 (SDF-1) and its receptor CXCR4." (PMID 40050933, 2025). "The CXCL12/CXCR4 axis is pivotal for triggering EMT, which is essential in drug resistance and tumour development in TNBC." (PMID 41002447, 2025). "ADSCs are recruited to the TME via tumor-secreted chemotactic signals, such as CCL2 and CXCL12, where they undergo functional reprogramming to adopt pro-tumorigenic roles." (PMID 40510466, 2025). "The cellular graph of the template patient contains diverse tumor cells, predominantly cytokeratin-positive cells, including CK8/18+ERhigh cells, CK8/18highCXCL12high cells, CK+CXCL12+ cells, and CKmedERlow cells." (PMID 40182181, 2025). "Compared to the oe‐NC+M2pep‐Cs NPs/Plerixafor group, CXCR4 mRNA expression in the tumor tissues of the oe‐CXCR4+M2pep‐Cs NPs/Plerixafor group was significantly upregulated; while, CXCL12 mRNA expression remained unchanged." (PMID 40536774, 2025).
tumor (continued). "A quantitative analysis confirmed that the CHL-GCS-IO NPs group exhibited the lowest CXCL12 levels, significantly lower than those in the other groups, highlighting the role of CHL-GCS-IO NPs in inhibiting factors that promote tumor progression and metastasis." (PMID 40514659, 2025). "Stromal C-X-C motif chemokine ligand 12 (CXCL12) retains C-X-C chemokine receptor 4 (CXCR4)-positive T cells in the stromal rim, limiting tumour entry." (PMID 41226286, 2025). "Our findings further revealed that tumor‐derived exosomes carrying CMTM4 potentiate the secretion of TGF‐β1 and CXCL12 through NF‐κB activation in TAMs." (PMID 40433989, 2025). "In mice with tumors of TNBC, PVT significantly reduced tumor growth and the expression levels of PTP1B, CXCL12, CXCR4, PI3K, AKT, mTOR and other proteins in TNBC tumor tissue and upregulated the expression of IL-24." (PMID 40076586, 2025). "Cell-cell communication is also of importance in shaping the TME, where metastatic survival depends on specific signaling (through CXCL12-CXCR4) between GPX4+ tumor and NOX4+TGFB1+CXCL12+ CAFs." (PMID 41450739, 2025). "CXCL12, primarily acting through its receptor CXCR4, is known to play a pivotal role in tumor growth, metastasis, and immune evasion." (PMID 40481962, 2025). "Endothelial cells and hepatic stellate cells (HSCs) produce chemokine (C-X-C motif) ligand 12 (CXCL12), which enhances intra-tumor myeloid cell migration by binding with the CXCR4 receptor, promoting tumor growth and immune suppression." (PMID 40869156, 2025). "DTP cells also actively reshape the tumor microenvironment (TME) by secreting IL-6, TGF-β, and CXCL12, which recruit immunosuppressive cells (e.g., TAMs, Tregs), thereby reinforcing drug tolerance and promoting tumor recurrence." (PMID 40894234, 2025). "In turn, activated CAFs secrete exosomes and soluble factors such as IL-6, CXCL12, and WNT-ligands, which induce JAK/STAT3 signaling in tumor cells and an enhanced PD-L1 expression, supporting immune evasion." (PMID 41439998, 2025). "Cytokines and chemokines activated by adrenergic signaling (IL-6, MIP-1α, TNFα, CXCL12/SDF-1) function as secondary mediators connecting sympathetic activity to osteoclast stimulation and tumor homing." (PMID 41465319, 2025). "The tumor microenvironment is rich in chemokines and cytokines, such as CXCL12 and EGF, that drive tumor progression and metastasis." (PMID 40796929, 2025). "CAFs play a central role by secreting CXCL12, which forms a chemokine barrier at the tumor periphery that restricts CD8+ T cell infiltration into the tumor core and impairs their spatial positioning." (PMID 41341574, 2025). "CXCL12, also known as stromal cell-derived factor-1 (SDF-1), is a chemokine involved in various physiological and pathological processes, including cell migration, inflammation, and tumor progression." (PMID 40481962, 2025). "Chemokines such as CXCL12, CXCL5 and CCL2 regulate tumor metabolism and promote a metabolic shift toward enhanced glycolysis and lipid metabolism to support rapid tumor growth, even under hypoxic conditions." (PMID 40134607, 2025). "CTCs exhibit the overexpression of CXCR4, while chemokine stromal cell-derived factor-1 (SDF-1, also known as CXCL12), which recruits and retains CXCR4+ cells, shows significant upregulation at the primary tumor site." (PMID 40725148, 2025). "Their functional maturation is promoted by cytokines such as IL4, IL6, IL13, and TNF, while mobilization into the tumor niche is orchestrated by chemoattractants including IL8, CCL2, and CXCL12." (PMID 41155172, 2025). "Previous studies have reported that HDAC inhibitors can modulate the tumor microenvironment by upregulating chemokines such as CXCL10 and CXCL12, thereby enhancing immune cell infiltration 35,36." (PMID 41049003, 2025). "TAMs also produce CXCL12, which binds to CXCR4 receptors on tumor cells, guiding their intravasation into lymphatic channels." (PMID 40647432, 2025).